OR4M2 (olfactory receptor family 4 subfamily M member 2)
Description:
Odorant receptor.
Synonyms: OR15-3
Tractability: Antibody: UniProt places it where antibodies can reach, with medium confidence; UniProt predicts a signal peptide or a membrane-spanning region; its Gene Ontology location is reachable by antibodies, with medium confidence.
Gene: Protein-coding gene on chromosome 15 (22,070,241 to 22,083,221, forward strand). Ensembl gene ENSG00000274102.
Subcellular location: Cell membrane
Pathways (Reactome):
Sensory Perception: Expression and translocation of olfactory receptors
Gene Ontology:
Molecular function: olfactory receptor activity; G protein-coupled receptor activity
Biological process: detection of chemical stimulus involved in sensory perception of smell; G protein-coupled receptor signaling pathway
Cellular component: plasma membrane; membrane
Homologues: Orthologues: macaque OR4M1 (94% identical), rat Or4m1 (88% identical), mouse Or4m1 (88% identical). Paralogues in human: OR4M2B (99% identical), OR4M1 (94% identical), OR4N5 (56% identical), OR4N2 (53% identical), OR4N4C (52% identical), OR4N4 (52% identical), OR4K1 (48% identical), OR4Q3 (48% identical), OR4K15 (47% identical), OR4D5 (47% identical), OR4E2 (47% identical), OR4K14 (47% identical), and 116 more.
Diseases named in the same sentence as OR4M2 in open-access papers:
OR4M2 is named in the same sentence as 2 diseases in open-access papers, as found by Europe PMC text mining. Sharing a sentence is not in itself a finding about the gene and the disease.
OR4M2 shares sentences with these, for which no sentence is quoted: ciliary dyskinesia (1 paper); glomerulosclerosis (1).